TRIM21 (tripartite motif containing 21)
Diseases named in the same sentence as TRIM21 in open-access papers (continued):
Sharing a sentence is not in itself a finding about the gene and the disease.
viral infection (continued). "One crucial immune escape strategy for virus infection is the negative regulation of immune responses via TRIM21 and its E3 ubiquitin ligase activity." (PMID 36675197, 2023). "Collectively, these data revealed that TRIM21 restricts viral infection in IRF1-dependent and IRF1-independent manners." (PMID 37327222, 2023). "In this study, we found that TRIM21 negatively regulates PKR-dependent translational shutdown upon viral infection or thapsigargin (TG) treatment." (PMID 37327222, 2023). "Recent results showed that TRIM21 participates in virus infection by directly interacting with viral proteins or modulating immune and inflammatory responses." (PMID 36675197, 2023). "Later, it was found that TRIM21 plays a crucial role in regulating the signal pathway of type I IFN during virus infection." (PMID 36675197, 2023). "Another E3 enzyme, tripartite motif-containing protein 21 (TRIM21), also targets the S protein to inhibit viral infection ability." (PMID 37360529, 2023). "We reintroduced wild-type PP1α (PP1α-WT) or K60-mutant PP1α (PP1α-K60R) together with pFlag-tagged TRIM21 into PP1α-silenced cells to detect the phosphorylation of PKR under viral infection or TG treatment." (PMID 37327222, 2023). "Apart from negatively regulating immune responses, TRIM21 also enhances immune responses during some virus infections." (PMID 36675197, 2023). "In this review, we discuss the recent progress on the mechanism of TRIM21 during virus infection and the application prospects of TRIM21 during virus infection." (PMID 36675197, 2023). "TRIM21 is upregulated both in vivo and in vitro during viral infection, significantly inhiting porcine reproductive and respiratory syndrome virus (PRRSV) replication." (PMID 37628607, 2023). "TRIM21 also decreases cytotoxic T cells induced by adenovirus-based vaccine and prevents the protective effect against subsequent virus infection." (PMID 36675197, 2023). "Taken together, the absence of TRIM21 within the cornea was not reflected by quantitative changes in ocular pathology, suggesting that TRIM21 plays little, if any, role in the host response to local virus infection and tissue pathology within the cornea." (PMID 35336995, 2022). "Three host proteins associated with viral infections, vimentin (VIM), tripartite motif-containing protein 21 (TRIM21), and Tu translation elongation factor (TUFM) interacted with D1133L in vitro." (PMID 36406406, 2022). "Under viral infection, Ro52 (so called TRIM21) is upregulated through the IFN/JAK/STAT signaling pathway, promoting innate immune response." (PMID 35962159, 2022). "We have discovered an effector mechanism in which anti‐N antibodies activate the cytosolic antibody receptor TRIM21 to mediate protection against viral infection." (PMID 33258165, 2021). "Two genes (IFIH1 and TRIM21) were upregulated in three viral infections; however, their expression was higher in SARS-CoV-2 compared to IAV, and RSV." (PMID 34276672, 2021). "B30.2 domain in the TRIM21 protein structure can identify the invading virus so that TRIM21 plays a vital role in the process of virus infection." (PMID 32373102, 2020). "Overall, our study identifies cytosolic TRIM21 as a positive regulator of CVB3-triggered MAVS-mediated type I Interferon signaling pathway that restricts viral infection." (PMID 30410495, 2018). "TRIM21 is critical for antibody-mediated control of virus infections in mice and is also active in human cells, though a role in virus infections of humans has not been clearly established." (PMID 28725225, 2017). "The primary role of TRIM21 is to sense intracellular antibodies during viral infection, but TRIM21 also activates innate immune signaling pathways, including NF-kB and IRFs20." (PMID 28592884, 2017). "The type-I IFNs, particularly IFN-β, produced in response to viral infection is suggested to be the main activators of TRIM21 expression involved in antibody-mediated intracellular neutralization." (PMID 27439689, 2016).
viral infection (continued). "Taken together, this data suggests that in order for TRIM21 to mediate neutralization and immune activation during viral infection, antibody must be present in the form of a virus-antibody immune complex." (PMID 27881870, 2016). "This has been reported in the case of Sendai virus infection, where TRIM21 acts as a positive regulator of the IRF3 pathway during viral infection." (PMID 24485101, 2014). "TRIM21 has been known to play a crucial role in regulating type I interferon production, but its role during viral infections is not well understood." (PMID 24485101, 2014). "TRIM21 is also induced by viral infection or Toll-like receptor (TLR) engagement via type I IFN induction." (PMID 22701487, 2012). "Infection experiments demonstrate that at physiological antibody concentrations TRIM21 neutralizes viral infection." (PMID 22701487, 2012). "TRIM21 is a multifunctional E3 ubiquitin ligase and intracellular antibody receptor, yet its role during viral infection remains unclear, with reports describing both antiviral and proviral activities." (PMID 41889827, 2026). "Specifically, nucleoprotein-specific NNAbs, commonly induced upon infection of enveloped viruses, have been demonstrated to confer protection via the TRIM21 pathway in many viral infections: lymphocytic choriomeningitis virus, adenoviruses, influenza virus, and paramyxoviruses." (PMID 40306326, 2025). "TRIM21 is an E3 ligase which gets activated upon viral infection by auto-ubiquitination." (PMID 38977311, 2024). "TRIM21 regulates a series of viral infections by affecting the innate immunity pathway." (PMID 38542289, 2024). "Given that TRIM21 suppresses PKR activation, we investigated whether TRIM21 can resist viral infection by promoting the protein synthesis of IRF1." (PMID 37327222, 2023). "Next, we examined whether this IFN-independent antiviral role of TRIM21 restricts viral infection by inhibiting PKR activation." (PMID 37327222, 2023). "Given that, we speculate that TRIM21 may have a role in restricting not only viral infection but also tumorigenesis via adaptive immunity, which needs further study." (PMID 37327222, 2023). "Moreover, the inhibition triggered by TRIM21 can synergize with complement-mediated inhibition of viral infection." (PMID 36675197, 2023). "To confirm our hypothesis, we constructed IFNAR1-deficient cell lines in both A549 cells (A549-sg-IFNAR1) and HLCZ01 cells (HLCZ01-sg-IFNAR1), as TRIM21 is able to inhibit viral infection by promoting IFN production." (PMID 37327222, 2023). "Moreover, TRIM21 also lost the ability to restrict viral infection by overexpression of TRIM21 in PKR/TRIM21 double-deficient Huh7.5 cells, suggesting that TRIM21 restricts viral infection via PKR." (PMID 37327222, 2023). "Taken together, TRIM21 targeting M1 is critical for TRIM21-mediated inhibition of virus infection." (PMID 37343022, 2023). "TRIM21 plays an important regulatory role in viral infection." (PMID 37446070, 2023). "TRIM21 regulates the innate immune response under viral infection through several mechanisms." (PMID 37446070, 2023). "Given the negative regulatory role of TRIM21 in PKR activation, we speculated that TRIM21 has the ability to restrict viral infection by inhibiting PKR-mediated translational shutdown." (PMID 37327222, 2023). "TRIM21 promotes IRF1 protein synthesis by inhibiting PKR activation upon viral infection." (PMID 37327222, 2023). "Our previous study showed that TRIM21, by catalyzing the K27-linked ubiquitination of mitochondrial antiviral signaling protein (MAVS), augments RIG-I/MDA5-mediated transcription of IFNs upon viral infection." (PMID 37327222, 2023). "Next, we examined the effects of TRIM21 on PKR signaling activation upon viral infection." (PMID 37327222, 2023). "Moreover, three randomly selected proteins associated with viral infections: VIM, TRIM21, and TUFM were confirmed to interact with D1133L by co-IP and IFA assays." (PMID 36406406, 2022).
viral infection (continued). "However, another study found TRIM21 stabilizes IRF3 expression resulting in an increase in resistance to virus infection; in this case, against Sendai virus." (PMID 35336995, 2022). "Furthermore, viral infection induces TRIM21 production in an IFN/Janus kinase/signal transducer and activator of transcription-dependent pathway, and loss of TRIM21 results in impaired innate immune responses." (PMID 36505476, 2022). "Anti‐N antibodies and TRIM21 could be clearing viral infection either cell autonomously or by synergising with cellular immunity." (PMID 33258165, 2021). "TRIM21 expression is up-regulated by CVB3 infection at early phase of viral infection." (PMID 30410495, 2018). "Recently, Xue et.al have reported that TRIM21 is upregulated upon RNA virus (SeV, VSV) infection, interacts with MAVS and catalyzes the K27-linked polyubiquitination of MAVS, thereby promoting the activation of IRF3 and inhibiting viral infection." (PMID 30410495, 2018). "Importantly, by using antibody/TRIM21 as a proxy marker for viral infection, the cell can detect infection at much lower multiplicity than virus in the absence of antibody." (PMID 31558002, 2016). "Indeed, TRIM21 was shown to interact directly with IRF3 upon viral infection and to interfere with its interaction with Pin1." (PMID 24586174, 2014). "However, TRIM21 has also been shown to stabilise IRF3 expression levels in response to sendai virus infection at the early phase of infection, thus indicating that the role of TRIM21 in IRF regulation is complex." (PMID 22479513, 2012). "Additionally, TRIM21 plays several roles in viral infections." (PMID 40277358, 2025). "In addition, TRIM21 initiates a signaling cascade that results in NF-κB activation and the subsequent production of proinflammatory cytokines during virus infection, and it inhibits HBV replication by triggering the proteasome degradation of the viral HBx protein." (PMID 40431659, 2025). "Additionally, tripartite motif-containing protein 21 (TRIM21), a member of the TRIM family with E3 ubiquitin ligase activity, has been implicated in viral infections through direct interactions with viral proteins or modulation of immune and inflammatory responses." (PMID 40612942, 2025). "This suggests that TRIM21 may act as an innate antiviral protein to combat viral infection." (PMID 38780244, 2024). "However, TRIM21 can also facilitate virus infection or immune escape for some viruses." (PMID 38932287, 2024). "Furthermore, TRIM21 can constitutively restrict viral infection by reversing PKR-dependent translational inhibition of various previously known and unknown antiviral factors." (PMID 37327222, 2023). "However, whether TRIM21 is able to restrict viral infection via regulation of the protein synthesis of antiviral effectors remains elusive." (PMID 37327222, 2023). "However, TRIM21 plays different roles in different virus infections." (PMID 35062360, 2022). "Thus, the antiviral activity of TRIM21 varies among different viral infection." (PMID 30410495, 2018). "In vitro experiments revealed that antibody-dependent intracellular neutralization of TRIM21 up-regulated by IFN-α was enhanced in adenovirus-infected Hela cells, and viral infection was inhibited." (PMID 39165359, 2024). "Intracellular antibody neutralization mediated by the cytosolic IgG receptor of TRIM21 enables TRIM-AWAY to be promising for controlling and preventing virus infection." (PMID 36675197, 2023). "Because dsRNAs produced during viral infection can activate PKR, we tried to test the function of TRIM21 during infection with a DNA virus, herpes simplex virus-1 (HSV-1)." (PMID 37327222, 2023). "Then, the E3 ubiquitin ligase activity of the TRIM21 RING domain can directly ubiquitinate virus protein, thus promoting viral protein to be degraded by the proteasome pathway and inhibiting virus infection." (PMID 36675197, 2023).
viral infection (continued). "Notably, TRIM21 interacted with PKR but not eIF2α, and the endogenous interaction between them was further confirmed in A549 cells, in which their interaction was enhanced upon viral infection or TG treatment, indicating that TRIM21 may inhibit PKR activation by targeting PKR." (PMID 37327222, 2023). "Collectively, the results of our study highlight a newly discovered biological role of TRIM21, and these data provide new evidence of PKR-mediated translational arrest in host resistance to virus infection." (PMID 37327222, 2023). "Additionally, viral infections are a trigger for various types of CTD, and TRIM21, as a cytosolic receptor for IgG antibodies, plays a crucial role in combating viral infections." (PMID 39165359, 2024). "However, the interaction between TRIM21 and DDX41 contributes to immune suppression during virus infection." (PMID 36675197, 2023). "Therefore, the ubiquitination of IRF3/7 or its upstream sensors by TRIM21, such as STING, DDX41, NMI/IFI35, and RIG-I, leads to immune suppression during virus infection." (PMID 36675197, 2023). "Up-regulated differentially expressed genes (DEGs) indicated a clear relationship with the innate immune response against viral infection, including genes coding PRRs (LPG2 or DHX58) and IFN-stimulated genes (ISG15, Mx, STAT1, HERC5, IFI44, IFIT-1, NUP133, TRIM21)." (PMID 35215144, 2022). "TRIM21 mediates the polyubiquitination and degradation of the DNA sensor DDX41 and the IRF transcription factors IRF3, IRF5, and IRF7 to negatively regulate the production of interferon-β during viral infection." (PMID 33061806, 2020). "Up to the present, there is no report of TRMI21 on CVB3 infection; and almost no biological function of TRIM21 has been confirmed in animal models of viral infection." (PMID 30410495, 2018). "Upon in vivo challenge with mouse adenovirus 1 (MAV-1), mice lacking TRIM21 succumb to fatal viral infection within 7 days." (PMID 26506431, 2015). "We hypothesized that the upregulation of TRIM21 in JEV-infected cells could be a mechanism toward counteracting the production of type I interferons and/or an antiviral response towards the virus infection." (PMID 24485101, 2014). "Therefore, TRIM21 has diverse activities during different virus infections, and its regulation of type I IFN and inflammatory reactions are inconsistent during various virus infections." (PMID 36675197, 2023). "Regarding upregulated DEGs, a clear relationship with the innate immune response against viral infection was observed, being unigenes detected those coding pattern recognition receptors (PRRs) (DHX58), and IFN-stimulated genes (ISG15, Mx, STAT1, HERC5, IFI44, IFIT-1, NUP133, and TRIM21)." (PMID 30065724, 2018). "In contrast to bacterial and viral infections, we show that TRIM21 impacts the formation of only K63 and not K48 ubiquitin chains at the vicinity of Toxoplasma PVs, concomitant with the activation of the innate immune signalling characterised by the production of inflammatory cytokines." (PMID 28701773, 2017). "Additional powerful biomarkers were identified for Pacific (Trim21, IFI) and Atlantic (CD9, RAD1, SACS, XAF1) salmon whereby assays did not work across species; if re-designed, these biomarkers may also contribute to the universal separation of viral disease states across species." (PMID 28702195, 2017).
breast carcinoma (47 papers, 2016 to 2025). "Western blotting showed that overexpression of TRIM21 in breast cancer cells caused a diminishing in the protein level of MTA1, whereas TRIM21 knockdown increased it." (PMID 39154024, 2024). "Its mutation eliminates TRIM21-mediated Snail ubiquitination and degradation, thereby increasing breast cancer cell migration and invasion." (PMID 38702792, 2024). "Consistent with our finding, R64Q mutation also decreased TRIM21-mediated invasion in breast cancer." (PMID 37771771, 2023). "For example, decreased TRIM21 expression in ovarian cancer, diffuse large cell lymphoma, and breast cancer is associated with shorter OS rates." (PMID 36982215, 2023). "It has been reported that the expression of TRIM21 was decreased in several malignant cancers, including colitis-associated cancer and breast cancer." (PMID 35662245, 2022). "Correspondingly, high TRIM21 expression rates were associated with increased survival rates of breast cancer patients." (PMID 35024438, 2022). "Decreased expression of TRIM21 has been found in hepatocellular carcinoma, diffuse large B-cell lymphoma and breast cancer, and was associated with a poor prognosis and enhanced proliferation capacity of cancer cells in vitro and tumor growth in vivo." (PMID 33937329, 2021). "TRIM21 depletion was associated with increased effects on the proliferation of breast cancer cells, which were partially attenuated by the simultaneous knockdown of SET7/9." (PMID 32102992, 2020). "TRIM21 functions as a tumor suppressor in breast cancer and high expression levels of TRIM21 are associated with longer overall survival of breast cancer patients." (PMID 31540324, 2019). "Of note, FAIM2 has been previously linked to TRIM21 in a breast cancer study." (PMID 35468884, 2022). "In colorectal and breast cancers, TRIM21 protein levels were frequently downregulated in colorectal and breast cancers." (PMID 40735642, 2025). "The inhibitory role of TRIM21 is also observed in the progression of other cancers, including gallbladder cancer, breast cancer and multiple mylenoma." (PMID 40379610, 2025). "In the present work, we confirm the role of TRIM21 as the E3 ligase to P27KIP1 in breast cancer cells." (PMID 39875724, 2025). "Here, we find that P27KIP1 degradation via E3 ligase TRIM21 is inhibited by human micropeptide hSPAR through its C-terminus (hSPAR-C), causing P27KIP1’s cytoplasmic accumulation in breast cancer cells." (PMID 39875724, 2025). "In breast cancer, TRIM21 mediated the ubiquitination and degradation of CCT2 to promotes CD4+T cell activation." (PMID 40735642, 2025). "Collectively, our data clearly demonstrate that TAT-hSPAR-C is necessary and sufficient for hSPAR-mediated cell proliferation inhibition and regulation on TRIM21/glutaimine-P27KIP1-mTOR axis in breast cancer cells." (PMID 39875724, 2025). "Our findings revealed that TRIM21 affects the stability of MTA1 to hinder breast cancer proliferation, invasion, EMT, and cancer stemness and synergizes with MTA3 to maintain epithelial homeostasis." (PMID 39154024, 2024). "The knockdown of Trim21 resulted in an increased proliferation rate and a decreased apoptotic rate in breast cancer cells." (PMID 39079960, 2024). "To assess the impact of Trim21 on breast cancer cell function, we first analyzed several publicly available datasets, and revealed that elevated Trim21 expression was associated with better OS, RFS, and DMFS in breast cancer patients." (PMID 39079960, 2024). "To explore the role of TRIM21 in breast cancer, we performed cell count assays, which revealed that increased breast cancer cell proliferation after TRIM21 knockdown, whereas overexpression of TRIM21 decreased their proliferation." (PMID 39154024, 2024).